LEP (leptin)
Diseases named in the same sentence as LEP in open-access papers (continued):
Sharing a sentence is not in itself a finding about the gene and the disease.
breast cancer (continued). "Leptin, a hormone mainly secreted by adipose tissue and involved in regulating body weight and pro-inflammatory response, can induce the expression of IL-1β, which upregulates downstream VEGF expression and signaling in breast cancer." (PMID 39858071, 2025). "Moreover, recent research has demonstrated that CD8+ effector T cells oxidize more fatty acids by the leptin STAT3 axis, which suppresses anti‐tumor immune responses in breast cancer." (PMID 38923758, 2024). "Leptin favors human epidermal growth factor receptor 2 (HER2) protein concentration through a STAT3-mediated mechanism and the upregulation of the heat shock protein (Hsp90) in breast cancer cells." (PMID 38785834, 2024). "Therefore, we assessed the effect of three concentrations of leptin (50, 200, and 400 ng/mL) on cell proliferation, cell morphology, and ERK phosphorylation of breast cancer cell lines." (PMID 38228661, 2024). "In addition to directly regulating breast cancer cells to increase VEGF expression in the tumor microenvironment, leptin can potently activate angiogenesis by acting directly on tumor endothelial cells." (PMID 39439572, 2024). "In particular, HIF-1α binds directly to the hypoxia response element (HRE) of the VEGFA promoter in mammary tumor cells, and when the HRE site was deleted from the VEGFA promoter in a luciferase reporter assay, leptin-induced luciferase signal was significantly reduced." (PMID 39439572, 2024). "Similarly, in breast cancer metastasis, BMAT secrete many factors including IL-1β and leptin which were shown to enhance migratory phenotype of breast cancer cells." (PMID 38625510, 2024). "Accordingly, we measured changes in cellular migration in highly invasive breast cancer cells (MDA-MB-231) which had high ATP production by glycolysis, treated with leptin, CQ, or oxidative phosphorylation (OXPHOS) inhibitors that prevent mitochondrial ATP formation (oligomycin and antimycin A)." (PMID 38228661, 2024). "In the mice receiving combination therapy, TQ and IF treated breast cancer in an additive way without causing liver or kidney toxicity due to decreased levels of glucose, IGF-1, and leptin and increased levels of β-hydroxybutyrate." (PMID 38202341, 2023). "Lower expression of adiponectin, AdipoR2, leptin and ObRs in the breast TME might be indicators of more aggressive breast cancer phenotypes." (PMID 37686525, 2023). "Leptin’s role in ASC-mediated tumor progression was demonstrated by the use of leptin silencing shRNA in obese ASCs, which prevented the enhanced proliferative effects of obese ASC on breast cancer cells following co-culture of ASCs with breast cancer cells." (PMID 36766689, 2023). "For instance, it was demonstrated that CCL2/monocyte chemoattractant protein-1, CCL5, IL-1β, IL-6, tumor necrosis factor α, vascular endothelial growth factor, and leptin released by CAAs in the TME promote the proliferation, and dissemination of breast cancer cells." (PMID 36980280, 2023). "Although the significant association between LEP, LEPR and ADIPOQ genes and breast cancer risk, we did not notice remarkable differences in circulating leptin levels across genotypes of their genetic alterations." (PMID 37274250, 2023). "Two studies with larger sample sizes (>100 participants), consistent with our finding, observed no significant change in leptin levels, indicating that the positive effect of exercise on leptin levels in breast cancer survivors is still unclear." (PMID 37571390, 2023). "In human breast cancer MCF-7 cells, leptin upregulates TF expression and increases its activity." (PMID 37686525, 2023). "When Leptin/AMPK signaling pathway is inhibited by acupuncture treatment, mitochondrial function damage can be reduced, thus improving fatigue after chemotherapy in breast cancer patients." (PMID 37542585, 2023). "By contrast, a recent meta-analysis by Sayad and coworkers did not support the association of LEP gene rs7799039 and LEPR gene rs1137100 with breast cancer." (PMID 37274250, 2023).
breast cancer (continued). "Although not explicitly studied in relation to breast cancer, leptin, which can increase estrogen levels, is increased in overweight and obese individuals." (PMID 37626871, 2023). "The median serum concentration of leptin was 48.86 ng/ml for the luminal breast cancer subtypes compared with 55.08 ng/ml for the non-luminal subtypes." (PMID 35989732, 2022). "In addition, body mass index (BMI) and leptin resulted correlated with pathological tumor classification (pT), tumor size, nodal and metastasis status (TNM) in postmenopausal breast cancer patients." (PMID 36361728, 2022). "In addition, the peptide LDFI recently showed to reduce cell-to-cell communication by decreasing LEP-dependent exosome biosynthesis in MCF-7 and triple-negative MDA-MB-23 breast cancer models." (PMID 36291602, 2022). "Besides, another study established that leptin elevates the expression levels of Twist and β-catenin, as well as the release of invasion markers MMP-2 and MMP-9 in breast cancer cells, leading to enhanced cell invasion in an SRC- and FAK-dependent way." (PMID 35379785, 2022). "In addition, we found that AMPK (involved LIPE and LEP) (p value = 0.003440464) and PPAR (involved PLIN1) (p value = 0.018732701) were two significantly enriched pathways in luminal A breast cancer." (PMID 35692369, 2022). "In addition, based on functional enrichment of DEmRNAs coexpressed with DElncRNAs, we found that AMPK (involved LIPE and LEP) and PPAR (involved PLIN1) were two significantly enriched pathways in luminal A breast cancer." (PMID 35692369, 2022). "Moreover, leptin is involved in the PI3K/AKT/lysyl hydroxylase signaling pathway, which facilitates breast cancer metastasis." (PMID 35073877, 2022). "Interestingly, inhibition of leptin signaling also decreased the vascular endothelial growth factor receptor 2 (VEGFR-2) expression levels in endothelial cells and breast cancer cells." (PMID 36010901, 2022). "Therefore, SAM68 not only mediates cell metabolism stimulated by insulin and leptin, but also participates in leptin- and insulin-dependent activation of MAPK and PI3K signaling pathways in breast cancer cells." (PMID 36059653, 2022). "In breast cancer leptin and LEPR expression is higher in tumor cells than in the normal breast epithelial cells and associated with tumor size and high tumor cell proliferation." (PMID 36077676, 2022). "Firstly, serum LEP levels in breast cancer patients and healthy women are not significantly different." (PMID 34414945, 2021). "Furthermore, leptin upregulates intracellular FFA levels and stimulates the use of fatty acid for ATP production via FAO induction in estrogen receptor (ER)‐positive breast cancer cells." (PMID 33226729, 2021). "Interestingly, a recent study has been suggested that leptin activates SREBP‐2 and thereby promotes migration and invasion of breast cancer cells via upregulation of acetyl‐CoA acetyltransferase 2 (ACAT2)." (PMID 33226729, 2021). "In conclusion, treatment with exemestane significantly lowered serum leptin levels in breast cancer patients while letrozole did not." (PMID 34554372, 2021). "We observed that leptin increases ER phosphorylation at serine residues 118 and 167 in breast cancer cells while no phosphorylation was observed at Ser-102/104/106, Ser-282, Ser-305, and Tyrosine-537 (null data not shown)." (PMID 34389732, 2021). "Alshaker and colleagues demonstrated that leptin as an adipokine was able to induce upregulation of SPHK1 and in turn SPHK1 could contribute to leptin-induced STAT3 activity in breast cancer via transactivation of IL-6/gp130." (PMID 34820423, 2021). "As expected, leptin‐induced ATP production was significantly inhibited by cotreatment with Etomoxir, suggesting that leptin uses fatty acid (FFA) for ATP production in breast cancer cells." (PMID 33226729, 2021).
breast cancer (continued). "Besides, both FAK and c-Src signaling stimulated the leptin-invadopodia of MCF10A normal breast epithelial cells and the migratory abilities of both MCF-7 and MDA-MB 231 breast cancer cells." (PMID 33562737, 2021). "Routine blood analyses, leptin, adiponectin, especially insulin, glucose, resistin, homeostatic model assessment (HOMA), monocyte chemoattractant protein-1 (MCP-1), age, and body mass index (BMI) data can also be used to diagnose breast cancer." (PMID 34730888, 2021). "Leptin increased ATP production in a time‐ and dose‐dependent manner in MCF‐7 breast cancer cells." (PMID 33226729, 2021). "In addition to promoting cancer cell metastasis through EMT, leptin can also promote the expression of lysine hydroxylase-2 (PLOD2) by activating the PI3K/AKT signaling pathway, thus promoting the metastasis of breast cancer." (PMID 34485124, 2021). "In fact, leptin has been found to upregulate antioxidant enzymes such as superoxide dismutase (SOD), catalase (CAT), and heme-oxygenase 1 (HO-1), but decreased lipid peroxidase in colorectal and breast cancer cells." (PMID 33535537, 2021). "Aiming at the protective barrier CNN5 of the breast, as a cytokine that can inhibit tumor growth and invasion, leptin can continuously inhibit the protective effect of CCN5 by activating the JAK/AKT/STAT signaling pathway, and promote the growth and progression of breast cancer." (PMID 34485124, 2021). "The role of the leptin-Ob-Rb signalling axis in cancer development is well documented with both leptin and OBR becoming overexpressed in several cancer types including head and neck, pancreatic, and breast cancer." (PMID 34572888, 2021). "Recent robust data demonstrating the role of leptin, IGF-1, adipocytokines, and obesity-related hormones in the pathology of breast cancer has clarified the possibility of disease prevention through lifestyle alteration and specific signaling-targeted inhibition." (PMID 34063828, 2021). "Leptin–LEPR signaling also cooperatively functions with other multiple signaling pathways, such as EGFR, Notch, IL-1, and the estrogen receptor, to enhance the proliferation, migration, invasion, and self-renewal activity of breast cancer stem cells." (PMID 34063828, 2021). "Although spontaneous FMC has been proposed as a suitable model for human breast cancer studies, the role of the leptin/ObR axis has never been evaluated in cats." (PMID 33644151, 2021). "Meanwhile, LEP (P = 2.68E−14, adjusted P = 7.06E−10, logFC = − 3.12) and FGF2 (P = 2.84E-14, adjusted P = 7.48E−10, logFC = − 1.87) were the two most significant down-regulated gene in breast cancer tissues." (PMID 34341433, 2021). "Recent evidence also indicates that leptin-stimulated breast cancer cells prefer using glucose for biosynthesis rather than energy production." (PMID 33535537, 2021). "Of note, leptin and Ob-R are overexpressed in breast cancer epithelial cells compared with non-cancer mammary epithelial cells." (PMID 34868066, 2021). "Another study also revealed that leptin elevated expression of SREBP-2 via PI3K/AKT signaling, thus upregulating acetyl-CoA acetyltransferase 2 (ACAT2) to favor the migration and invasion of breast cancer cells." (PMID 34888248, 2021). "Even a combined analysis of a serum panel of potential breast cancer markers, consisting of osteopontin, haptoglobin, haptoglobin, CA153, CEA, CA-125, prolactin, CA19-9, α-fetoprotein, leptin and migration inhibitory factor, is unable to predict the presence of early-stage breast cancer." (PMID 33803633, 2021). "Studied polymorphisms of the LEP and LEPR genes do not increase breast cancer risk in the population of Polish women." (PMID 33864589, 2021). "The results showed that the Free Leptin Index is significantly decreased in cats with mammary carcinoma (p = 0.0006), particularly in those with luminal B and HER2-positive tumors, and that these animals also present significantly lower serum leptin levels (p < 0.0001 and p < 0.005, respectively)." (PMID 33644151, 2021).
breast cancer (continued). "Indeed, cats with mammary carcinoma showed a decreased FLI, coupled with decreased serum leptin levels in animals with luminal B or triple-negative mammary carcinoma subtypes." (PMID 33644151, 2021). "FAM83H-AS1 deregulation is associated with migration and cell death impairment in BRCA samples and breast cancer cells, and may regulate a plethora of cancer-related gene targets, such as p63, BAX, LEP and CLDN1." (PMID 32839509, 2020). "Moreover, it has been reported that estradiol administration increases leptin and OBR expression in ER-positive MCF-7 breast cancer cell line." (PMID 32471192, 2020). "Without an estrogen ligand, leptin can activate the estrogen receptor (ER) signaling resulting in the growth of breast cancer cells." (PMID 33123472, 2020). "Furthermore, adipocyte- or CAA-secreted factors, including leptin, TNF-α, IL-6, IL-1β, IGFBP-2, LCN2, collagen VI, and others, have also been demonstrated to promote breast cancer cell malignant progression, such as EMT, invasion, and metastasis." (PMID 32242230, 2020). "Several signaling pathways have been demonstrated to enhance proliferative of breast cancer cells, including the activation of JAK/STAT3 and PI3K/Akt by leptin, as well as JAK2 activation-mediated human epidermal growth factor receptor-2 (HER2) transactivation." (PMID 33123472, 2020). "Interestingly, adipocytes and CAAs in breast cancer stroma have been shown to induce cancer cell EMT through soluble factors such as IL-6 and leptin, both of which activate Stat3 signaling and promote cancer cell migration and invasion." (PMID 32242230, 2020). "Hence, the leptin and CXCL12 activated miR-218/Wnt loop fuels Wnt signaling to enhance expression of metastatic and osteomimetic genes in aggressive breast cancer cells that home to bone." (PMID 33123472, 2020). "Associations between leptin mRNA and FGFR1 mRNA expression are positive in breast tumor-adjacent tissue (Rho = 0.26) and primary breast cancer tissue (Rho = 0.16), and negative in normal breast tissue (Rho = −0.27)." (PMID 33019728, 2020). "The pattern of tissue distribution of KHDRBS1, leptin, and LEPR in bone metastases from breast cancer is unknown." (PMID 33213024, 2020). "In addition, we revealed that leptin/OBR mediated the regulation of PAI-1 through the interactions between adipocytes and breast cancer cells." (PMID 33371368, 2020). "One report demonstrated that a high expression of LepR in breast cancer tissue predicts poorer outcomes in patients with high, but not low, sera leptin." (PMID 33019728, 2020). "Since E0771 breast cancer cells have been shown not to produce leptin, even when co-cultured with adipocytes, it therefore does not significantly contribute to increased leptin levels." (PMID 32257945, 2020). "The leptin/ObR axis through the activation of JAK2/STAT3, MEK, and PI3K/Akt signalings intimately controls different cellular activities, including mitogenesis, survival, transformation, migration, and invasion of breast cancer cells." (PMID 32260113, 2020). "Besides, the leptin (LEP) level was significantly positively correlated with LEPR and PAI-1 levels in breast cancer tissues via the TCGA dataset." (PMID 33371368, 2020). "The present studies indicate that leptin and CXCL12 may upregulate the Wnt/β-catenin pathway in breast cancer." (PMID 33123472, 2020). "The leptin/LEPR/KHDRBS1 axis, whose components have been studied in breast cancer, may also be expressed in metastatic tissue and contribute to colonization." (PMID 33213024, 2020). "Moreover, IL-6 or leptin can increase procollagen-lysine, 2-oxoglutarate 5-dioxygenase 2 (PLOD2) expression in breast cancer cells through the activation of the JAK/STAT3 and the AKT signalling pathway." (PMID 32033341, 2020).
breast cancer (continued). "The relationship between adiposity and breast cancer might be explained partly by biological effects of the adipokines, ADIPOQ, and LEP, which are secreted by adipocytes." (PMID 32046756, 2020). "Leptin is usually absent in nonneoplastic tissue; however, recent studies demonstrated that, leptin was also secreted by CAFs in breast cancer." (PMID 31119158, 2019). "Starting from these experimental conditions, we analyzed the number and the size distribution of vesicles, isolated from the conditioned media of MCF-7 and MDA-MB-231 breast cancer cells treated or not with leptin 500 ng/mL for 48 h, using NTA." (PMID 31336913, 2019). "However, there are still gaps in our understanding on the mechanisms by which leptin contributes to EMT and during the onset of breast cancer." (PMID 31554180, 2019). "These metabolic reprogramming adaptations induced by leptin may provide benefits for MCF-7 growth and could contribute, together with other factors, to the worse prognosis of breast cancer in obese women." (PMID 31052256, 2019). "In addition, leptin participates in the phosphorylation of VEGFR-2 (VEGF type 2 receptor) independently of VEGF in endothelial cells and breast cancer cells." (PMID 31380268, 2019). "The role of leptin, a major adipokine secreted by adipose tissue, has been largely investigated and we have shown that it stimulates the proliferation of breast cancer cells but not that of normal cells." (PMID 31756890, 2019). "For instance, patients with breast cancer who have high levels of leptin but with negative expression of estrogen hormone receptor have a higher survival rate." (PMID 31380268, 2019). "Particularly, we identified a novel role for leptin in inducing the generation of exosomes from both estrogen receptor-(ER) and progesterone receptor-(PR) positive MCF-7 and in ER-, PR-, and HER2-negative MDA-MB-231 breast cancer cell lines." (PMID 31336913, 2019). "Accordingly, when leptin activity was inhibited by using the full leptin receptor antagonist, the peptide LDFI, both Tsg101 expression and the amount of exosomes released by leptin-treated breast cancer cells were reduced." (PMID 31336913, 2019). "First, we performed time-course assays to establish whether leptin induces FAK phosphorylation and activation in MDA-MB-231 and MCF7 breast cancer cell lines." (PMID 31671408, 2019). "Mechanistically, adipocyte-derived interleukin-6 (IL-6) and leptin may facilitate PLOD2 upregulation in breast cancer cells and promote breast cancer metastasis in tail vein metastasis assays." (PMID 30563531, 2018). "Moreover, the secretion of IL-6 and leptin was significantly higher in the supernatant of MDA-MB-231 and MDA-MB-468 breast cancer cells after adipocyte coculture as compared with MDA-MB-231 and MDA-MB-468 cells grown alone." (PMID 30563531, 2018). "To further confirm whether IL-6 and leptin could induce PLOD2 expression, we treated MDA-MB-231 and MDA-MB-468 breast cancer cells with recombinant human IL-6 protein." (PMID 30563531, 2018). "Finally, we showed that IL-6 (5 ng/ mL) and leptin (50 ng/ mL) significantly increased the migration of MDA-MB-231 and MDA-MB-468 breast cancer cells." (PMID 30563531, 2018). "Furthermore, we showed that ER inhibition abolished leptin-induced AMPK phosphorylation and FoxO3A expression in breast cancer cells." (PMID 29312618, 2017). "In addition, we identified the influence of Leptin and SAHA treatment on the acetylation levels of AcH3 and AcH4 residues binding with p21WAF1/CIP1 promoter in breast cancer cells." (PMID 27926517, 2017). "In addition, leptin prevents ubiquitination and degradation of ER induced by ICI-182, 780, an anti-estrogenic modulator, in breast cancer cells and thereby develops resistance to anti-estrogen therapy." (PMID 29312618, 2017). "The same authors reported that higher leptin levels are more strongly correlated with ER+ breast cancer rather than ER−." (PMID 28861689, 2017).